APOD (apolipoprotein D)
Description:
APOD occurs in the macromolecular complex with lecithin-cholesterol acyltransferase. It is probably involved in the transport and binding of bilin. Appears to be able to transport a variety of ligands in a number of different contexts.
Synonyms: Apo-D
Tractability: Small molecule: a structure with a bound ligand is known; it has a high-quality binding pocket. Antibody: its Gene Ontology location is reachable by antibodies, with high confidence; UniProt places it where antibodies can reach, with medium confidence; UniProt predicts a signal peptide or a membrane-spanning region; the Human Protein Atlas places it where antibodies can reach.
Gene: Protein-coding gene on chromosome 3 (195,568,705 to 195,584,033, reverse strand). Ensembl gene ENSG00000189058.
Subcellular location: Secreted
Subcellular location (Human Protein Atlas): Plasma membrane; Predicted to be secreted
Pathways (Reactome):
Signal Transduction: NR1H3 & NR1H2 regulate gene expression linked to cholesterol transport and efflux
Transport of small molecules: Transport of fatty acids
Gene Ontology:
Molecular function: cholesterol binding; protein binding; lipid transporter activity; lipid binding
Biological process: glucose metabolic process; lipid metabolic process; negative regulation of cytokine production involved in inflammatory response; negative regulation of focal adhesion assembly; negative regulation of lipoprotein lipid oxidation; negative regulation of monocyte chemotactic protein-1 production; negative regulation of platelet-derived growth factor receptor signaling pathway; negative regulation of protein import into nucleus; negative regulation of smooth muscle cell proliferation; negative regulation of smooth muscle cell-matrix adhesion; negative regulation of T cell migration; response to reactive oxygen species; angiogenesis; peripheral nervous system axon regeneration; response to axon injury; tissue regeneration; brain development; lipid transport; response to stress
Cellular component: extracellular exosome; extracellular region; perinuclear region of cytoplasm; cytosolic ribosome; dendrite; neuronal cell body
Genetic constraint (gnomAD): Loss-of-function variants: 22 observed, 21.87 expected, observed/expected ratio (o/e) 1.01, 90% interval 0.72 to 1.44. The upper end of that interval is the gene's LOEUF score, 1.44, which puts it in group 5 of 6, group 1 being the genes least tolerant of losing a copy. Missense variants: 223 observed, 242.53 expected, observed/expected ratio (o/e) 0.92, 90% interval 0.82 to 1.03. Synonymous variants: 97 observed, 97.08 expected, observed/expected ratio (o/e) 1, 90% interval 0.85 to 1.18.
Homologues: Orthologues: chimpanzee APOD (97% identical), macaque APOD (87% identical), pig APOD (81% identical), dog APOD (78% identical), guinea pig APOD (77% identical), rabbit APOD (77% identical), mouse Apod (72% identical), rat Apod (72% identical), zebrafish apodb (49% identical), zebrafish apoda.1 (44% identical).
Diseases named in the same sentence as APOD in open-access papers:
APOD is named in the same sentence as 149 diseases in open-access papers, as found by Europe PMC text mining. Sharing a sentence is not in itself a finding about the gene and the disease. The quoted sentences say what the papers report.
Alzheimer disease (29 papers, 2006 to 2025). A progressive, neurodegenerative disease characterized by loss of function and death of nerve cells in several areas of the brain leading to loss of cognitive function such as memory and language. "ApoD levels increase significantly with aging and are linked to neurodegenerative and neurological conditions, including Alzheimer’s disease." (PMID 40137160, 2025). "More recent studies have sown that loss of apoD in the APP/PS1 amyloidogenic Alzheimer’s disease (AD) mouse model significantly worsens AD pathology, whereas neuronal expression of human apoD in the same AD mouse model reduces AD pathology." (PMID 26829325, 2016). "As with apoE, certain alleles of apoD have been linked to an increased risk of developing Alzheimer's disease." (PMID 25513803, 2014). "Variations in APOD gene were associated with an increased risk of early onset of Alzheimer's disease in a group of Finns." (PMID 16507104, 2006). "The fact that EV-associated human ApoD is detected both as monomers and dimers, is a readout of its antioxidant activity, since it is known that a consequence of its lipid reducing activity is the formation of stable dimers that accumulate in advanced stages of Alzheimer’s disease patients." (PMID 30687015, 2018). "In addition, the significant 12.57 fold increase in apolipoprotein D might indicate susceptibility for Alzheimer's disease in our examined human SN cells." (PMID 22163301, 2011). "It discusses the evidence for the multifaceted roles of ApoD in the mechanisms and pathogenesis of multiple sclerosis, Alzheimer’s disease, and Parkinson’s disease." (PMID 39767175, 2024). "The APOD gene is upregulated in a number of pathologies, including Alzheimer’s disease, Parkinson’s disease, cancer, and hypothyroidism." (PMID 37237893, 2023). "ApoD’s involvement in Alzheimer disease has been known for almost three decades, when it was first observed that its level in the cerebrospinal fluid and hippocampus of Alzheimer’s patient was more than 3× higher than normal." (PMID 37237893, 2023). "Human apolipoprotein-D (apoD) is a glycosylated lipocalin that plays a protective role in Alzheimer’s disease due to its antioxidant function." (PMID 33399852, 2021). "APOD is mainly expressed in glia and neurons and is elevated in some other neurological disorders such as Alzheimer’s disease, specifically in the CSF, in multiple sclerosis, in the aging brain and in neuronal tissues from Niemann Pick C disease." (PMID 33478506, 2021). "Oxidation of Met-93 in vitro leads to apoD dimer formation and these dimers are also observed in the brain of Alzheimer's disease patients, a function unique to apoD in the lipocalin family." (PMID 33399852, 2021). "ApoD is an acid glycoprotein and is elevated in disease states such as prostate cancer and Alzheimer’s disease." (PMID 32138228, 2020). "Previous studies reported that ApoD was upregulated in many nervous system diseases (Alzheimer’s disease, Parkinson’s disease, and stroke)." (PMID 32771037, 2020). "Recent studies have shown that cerebral apoD levels increase with age and in Alzheimer’s disease (AD)." (PMID 26829325, 2016). "Another identified gene, apolipoprotein D (Apod), has a role in the aging brain and in Alzheimer's dementia." (PMID 25063768, 2014). "Elevated levels of ApoD have also been noted in human plasma during a first psychotic episode, as well as in patients with bipolar disorder, Parkinson's and Alzheimer's diseases." (PMID 24558408, 2014). "The concentration of apoD also increases in the brain, and to some extent in plasma, as a result of ageing and of brain disorders such as Alzheimer's disease, stroke or brain infections." (PMID 25513803, 2014). "Interestingly, it has also been shown that Apolipoprotein E (ApoE), an apolipoprotein involved in lipid and cholesterol transport and Alzheimer’s disease, specifically the isoforms E3 and E4, can bind and repress ApoD expression." (PMID 37237893, 2023).
Alzheimer disease (continued). "ApoD has an antioxidant function and plays a protective role in Alzheimer’s disease." (PMID 33399852, 2021). "ApoD is known to be upregulated in astrocytes during aging and in various neurological disorders including schizophrenia, bipolar disorder, stroke, Alzheimer’s disease (AD), Parkinson’s disease (PD), and Niemann-Pick’s C disease." (PMID 30467822, 2019). "The ApoD gene has been thoroughly studied in human and mice, and its abnormal expression was reported to be related to human diseases, such as Parkinson’s disease and Alzheimer’s disease." (PMID 30621595, 2019). "Moreover, apolipoprotein D is upregulated at the protein level in the aging human brain and to a greater extent in a variety of neurological diseases, including Alzheimer's disease." (PMID 18830410, 2008). "While APOD is significantly downregulated in CE skin fibroblasts when compared to control females, the increased expression of APOD was found in patients affected by a variety of disorders, including schizophrenia, Alzheimer’s disease, Parkinson’s disease, bipolar disorder, and multiple sclerosis." (PMID 34575929, 2021). "Interestingly, while ApoD is known to be increased in the CSF of patients with Alzheimer’s disease, its plasmatic levels do not appear to be affected." (PMID 33923459, 2021).
breast carcinoma (29 papers, 1996 to 2025). "It was reported that APOD was significantly downregulated in hepatocellular carcinoma, colorectal cancer, epithelial ovarian cancer, and breast cancer, and was closely associated with tumor progression and poor prognosis in these cancer types." (PMID 37296697, 2023). "Apolipoprotein D (ApoD), a protein regulated by androgen and estrogen, is implicated in breast cancer as a poor prognostic factor." (PMID 36389725, 2022). "The distribution of exchangeable apolipoproteins, such as apoC-I, apoC-II, apoC-III, apoD, between lipoproteins is linked to the severity of breast cancer." (PMID 35268435, 2022). "Many studies have demonstrated that APOD expression is correlated with various tumors, such as breast cancer and colorectal cancer, and is significantly associated with GC risk assessment." (PMID 34308747, 2021). "In both the ER+/TAM+ and ER–/TAM– strata, all matched associations between ApoD and breast cancer recurrence were near null in both the ER+/TAM+ and ER–/TAM– strata." (PMID 28301514, 2017). "According to previous studies, APOD was an immune-related gene and is associated with the risk of multiple types of cancer such as gastric cancer, thyroid cancer, breast cancer and cervical cancer, which was also considered as one of prognostic signatures in cancer." (PMID 36536343, 2022). "For example, apoD and apoE in serum are viewed as risk factors for breast carcinoma." (PMID 32306242, 2020). "believe that the true association between APOD expression and recurrence may be ineffective in ER+ breast cancer patients treated with tamoxifen." (PMID 31781173, 2019). "Associations between ApoD expression and breast cancer recurrence within strata*." (PMID 28301514, 2017). "In breast cancer, ApoD is reported to inhibit the translocation of phosphorylated MAPK into the nucleus, reducing the proliferation of cancer cells." (PMID 38673873, 2024). "In breast cancer cells, retinoic acid induces an increase in ApoD, and this elevated expression is a good prognostic marker in breast cancer." (PMID 38673873, 2024). "Changes in APOD concentration are influenced by breast cancer metastasis and invasion, but older breast cancer patients also have increased levels compared to younger patients." (PMID 38067270, 2023). "A recent study concluded that the APOD gene was significantly reduced in breast cancer patients and displays an anti-tumor effect by suppressing MAPK, leading to a restriction in cell mitosis." (PMID 38067270, 2023). "While apoD has been shown to inhibit the proliferation of breast cancer cells, estrogens significantly reduce apoD gene expression." (PMID 35268435, 2022). "Low APOD expression predicts poor prognosis in colorectal cancer, ovarian cancer, and breast cancer." (PMID 36467500, 2022). "Low expression level of APOD is predictive of unfavorable prognosis in many cancer types, for instance, colorectal cancer, ovarian cancer and breast cancer." (PMID 35184747, 2022). "One study pointed out that APOD was most highly expressed in benign tumours and least expressed in invasive cancer and breast cancer with metastasis." (PMID 36243728, 2022). "In the present study, we showed that plasma apoD is higher in the case of high proliferative index tumors, only in the case of RH- breast cancer tumors." (PMID 35268435, 2022). "This study found that high APOD expression is related to longer survival, which is consistent with a previous breast cancer signature." (PMID 36243728, 2022). "Nevertheless, women with advanced breast cancer were shown to have higher plasma concentrations of apoD, and apoD was suggested to be a good prognostic indicator for the disease." (PMID 35268435, 2022). "ApoD is probably one of the apolipoproteins that were the most extensively studied in the context of breast cancer." (PMID 35268435, 2022).
breast carcinoma (continued). "Apolipoprotein D (APOD) has been determined to be a predictor of breast cancer recurrence among tamoxifen-treated patients with estrogen receptor positivity (ER+)." (PMID 34178625, 2021). "Researchers found that high expression of APOD was correlated with worse survival outcome of breast cancer patients." (PMID 33492335, 2021). "APOD is an apolipoprotein, and recent studies have shown that it can be used as a prognostic marker for breast cancer." (PMID 34195091, 2021). "Our study did not consider the patients’ different treatment, and it showed APOD expression has a good prognosis value in Luminal A breast cancer." (PMID 31781173, 2019). "Apolipoprotein D (ApoD) has been proposed as a predictor of breast cancer recurrence among estrogen receptor-positive (ER+), tamoxifen-treated patients." (PMID 28301514, 2017). "Immunohistochemical expression of the androgen-regulated glycoprotein, apolipoprotein D (apo-D), was also evaluated in the breast cancer specimens." (PMID 8883401, 1996). "APOD overexpression was correlated with poor prognosis in GC and breast cancer." (PMID 40406134, 2025). "Women with advanced breast cancer were shown to have higher plasma concentrations of apoD." (PMID 35268435, 2022). "It was also suggested that apoD expression could be predictive of breast cancer recurrence in tamoxifen-treated patients." (PMID 35268435, 2022). "Apolipoprotein D (APOD) is associated with the prognoses of prostate cancer and breast cancer." (PMID 33680915, 2020). "Cox proportional hazard model demonstrated a hazard ratio of 0.9 (p < 0.05) for APOD, suggesting that each unit increase in its expression is linked to a 10% reduction in risk of non-response, indicating a potential protective role in breast cancer." (PMID 41366282, 2025). "Moreover, it has been shown that APOD can inhibit the proliferation of cancer cells in breast cancer, prostate cancer, and colorectal cancer cell lines, and it may be used as a marker of the initial stage of tumor deterioration." (PMID 34221185, 2021). "Osteopontin-a upregulates the levels of glucose in breast cancer cells through STAT3, likely via its transcriptional targets apolipoprotein D and IGFBP5." (PMID 38039408, 2023). "An AA metabolic signature (SPINK8, KLRB1, APOD and PIGR) was constructed for breast cancer prognosis." (PMID 36243728, 2022). "In another study, a signature of four immune-related genes (APOD, CXCL14, IL33, and LIFR) was correlated with breast cancer prognosis." (PMID 33092068, 2020). "However, when calculating the ratio between apoD and apoA-I in HDL, these differences disappeared, suggesting that the relationship between HDL apoD and RH- breast cancer severity is due to an increased number of HDL particles carrying apoD, and not to a relative enrichment of HDL in apoD." (PMID 35268435, 2022). "The increased expression of APOD could predict poor prognosis in patients with breast cancer independent of the expression of ER α and AR." (PMID 34983559, 2022). "These variations of APOD mRNA level between obese non-pregnant women and obese pregnant women might be driven by estradiol regulation on APOD expression, as circulating estradiol concentration increases during pregnancy and downregulates APOD expression in breast cancer." (PMID 34638803, 2021).
Parkinson disease (14 papers, 2014 to 2024). A progressive degenerative disorder of the central nervous system characterized by loss of dopamine producing neurons in the substantia nigra and the presence of Lewy bodies in the substantia nigra and locus coeruleus. "Apolipoprotein D (ApoD) is a secreted glycoprotein and is found to be associated with various neurological disorders such as Alzheimer’s and Parkinson’s diseases." (PMID 32709043, 2020). "Another gene includes APOD, which in humans has been shown to be elevated in individuals with Alzheimer's and Parkinson's." (PMID 39119785, 2024). "In the same way, apolipoprotein D was significantly related to age and to Parkinson’s disease." (PMID 37108152, 2023). "APOD and APOE have also been implicated in Parkinson’s disease." (PMID 33478506, 2021). "Parkinson's disease stage and ApoD are significantly correlated." (PMID 29780571, 2018). "Therefore, increasing the ApoD level in substantia nigra neurons could offer a promising avenue for treating Parkinson’s disease patients." (PMID 39767175, 2024).
Obesity (13 papers, 2009 to 2025). Accumulation of substantial excess body fat. "Previous reports have shown that NLaz affects longevity, stress resistance, and metabolism in Drosophila, and ApoD has been linked to obesity and insulin resistance, but the role of ApoD in diabetes and metabolic disorders remains to be clarified." (PMID 39033139, 2024). "In conclusion, the damage caused by BPA can be repaired by upregulation of APOD and it is a potentially effective biochemical detection indicator for the treatment of obesity or NAFLDs caused by BPA exposure." (PMID 37755785, 2023). "APOD is a potential effective agent for the treatment of obesity and NAFLD caused by BPA exposure." (PMID 37755785, 2023). "However, a role for ApoD in mediating inflammation has been characterized in the nervous system and in various pathologies, such as disorders associated with obesity." (PMID 37237893, 2023). "Up-regulation of APOD, in conjunction with gene expression patterns consistent with increased estrogen and inflammatory signaling, suggest potential molecular mechanisms underlying the increased risk for obesity and metabolic syndrome in offspring of obese women." (PMID 24558408, 2014). "In recent studies of diet-induced obesity, ApoD has been shown to modulate lipid mediators derived from ARA, but also from eicosapentaenoic acid and docosahexaenoic acid in an anti-inflammatory way." (PMID 37237893, 2023). "We have demonstrated that in the round ligament of morbidly obese women (BMI of over 40), a specific hepatic adipose deposit highly developed during obesity, the level of ApoD is inversely correlated to the inflammatory profile of the patients." (PMID 37237893, 2023). "Further studies are needed to clarify the role of APOD in metabolic diseases, especially in obesity and type 2 diabetes, including men." (PMID 34638803, 2021). "Future experiments are planned to study fetal brain apoptosis, APOD gene expression, and offspring neurocognitive development in a mouse model of maternal diet-induced obesity." (PMID 24558408, 2014). "ApoD dysregulation may contribute to metabolic abnormalities ininsulin resistant subjects with obesity and/or type 2 diabetes." (PMID 19946382, 2009). "Since ApoD expression is upregulated in numerous diseases, it might serve as a therapeutic agent against pathologies aggravated by OS and inflammation such as many obesity comorbidities." (PMID 37237893, 2023). "Together, the depletion of APOD and PRDX2 highlights a broader impairment in the antioxidative and anti-inflammatory functions of adiposome cargo in obesity." (PMID 40981199, 2025). "Collectively, the reciprocal shift from protective proteins like TTR, APOD, and PRDX2 to pro-inflammatory mediators such as CRP and C9 highlights a coordinated reprogramming of adiposome cargo in obesity." (PMID 40981199, 2025). "FA treatment decreased mRNA of ApoD, SEMA3C, CXCL12, and sFRP2, which are closely related to adipocyte differentiation and obesity." (PMID 33915783, 2021).